BDNF (brain derived neurotrophic factor)
Diseases named in the same sentence as BDNF in open-access papers (continued):
Sharing a sentence is not in itself a finding about the gene and the disease.
epilepsy (continued). "Furthermore, our study elucidated that interfering BDNF reverses the activation of astrocytes and the hippocampal neuron injury in epilepsy rats by downregulating miR-103a expression." (PMID 31049031, 2019). "Seizures also increased hippocampal and cortical BDNF protein levels in animal model of epilepsy." (PMID 30117106, 2019). "However, there is a need for further researches to better understand the role of BDNF in epilepsy, especially regarding its role in modulation of inflammatory processes." (PMID 30117106, 2019). "Uncovering the mechanism of this novel form of BDNF signaling in the brain may provide a new direction for epilepsy therapeutics and open a window into the complex mechanisms of STAT3 transcriptional regulation in neurological disease." (PMID 31455240, 2019). "Collectively, this present study supports that inhibition of miR-103a can inhibit the activation of astrocytes in hippocampus tissues of epilepsy rats and improve the pathological injury of neurons, and the mechanism of which is related to targeted regulation of BDNF gene." (PMID 31049031, 2019). "BDNF is involved in numerous functions and phenotypic traits, in particular, stress and epilepsy." (PMID 31331937, 2019). "Therefore, our study is supposed to investigate the role of miR-103a in epilepsy by regulating the expression of BDNF." (PMID 31049031, 2019). "At the same time, some experts reported that in the model of epilepsy induced by pilocarpine, the increase of BDNF concentration could inhibit the occurrence of epilepsy." (PMID 31049031, 2019). "Compared with miR-103a inhibitors alone, epilepsy rats treated with BDNF-siRNA combined with miR-103a inhibitors significantly increased expression of GFAP in hippocampal tissues of epilepsy rats, increased number of apoptotic neurons and significantly decreased the number of surviving neurons." (PMID 31049031, 2019). "Furthermore, seizures dramatically increase mRNA levels and protein expression of the brain-derived neurotrophic factor (BDNF) both in epilepsy animal models and humans with epilepsy." (PMID 31827499, 2019). "We previously found that neurons respond to prolonged BDNF exposure (both in vivo (in models of epilepsy and TBI) and in vitro (in BDNF treated primary neuronal cultures)) by activating the Janus Kinase/Signal Transducer and Activator of Transcription (JAK/STAT) signaling pathway." (PMID 31455240, 2019). "While levels of BDNF in the circulation may show variable changes in human patients with epilepsy, our recent study and a previous report both showed significantly decreased levels of serum BDNF in adult patients with epilepsy." (PMID 30524358, 2018). "Knockdown of the BDNF gene has been shown to prevent the development of epilepsy." (PMID 30356026, 2018). "In the present study, we tested the hypothesis that the neurotrophic factors IGF-1 and BDNF play a crucial role in the regulation of autonomic functions and cerebral autoregulation in patients with epilepsy." (PMID 30524358, 2018). "In another study, no child with a heterozygous (Val/Met) BDNF polymorphism developed epilepsy earlier than 2 years." (PMID 29321033, 2018). "Our recent study found that lower serum levels of BDNF may indicate a longer duration of epilepsy, impaired white matter integrity, and poor cognitive function in patients with chronic temporal epilepsy." (PMID 30524358, 2018). "BDNF is one of the main actors of epileptogenesis and of epilepsy-induced neurogenesis." (PMID 29721159, 2018). "ERK1 is regulated by the BDNF/TrkB signaling pathway, and the TrkB signaling pathway is activated during seizure induction has been demonstrated in varies epilepsy animal models including PTZ model." (PMID 30186110, 2018). "The present results demonstrated that inhibition of Kir4.1 channels facilitates BDNF expression in astrocytes primarily by activating the Ras/Raf/MEK/ERK pathway, which may be linked to the development of epilepsy and other neuropsychiatric disorders." (PMID 29358904, 2017).
epilepsy (continued). "BDNF preprocessing catabatic TrkB receptor activation can partially reduce high frequency discharge, but the excessive expression of miR-132 deteriorates the symptoms of epileptic discharge, proving the control of miR-132 on the BDNF/TrkB signaling pathway as an important mechanism of epilepsy." (PMID 29118714, 2017). "Several groups have previously evaluated the levels of BDNF in epilepsy models." (PMID 27057559, 2016). "The expression of BDNF and its connection with miR-155 production in epilepsy were also determined." (PMID 27303295, 2016). "Previous studies demonstrated an increase of BDNF in epilepsy patients: the molecule could induce epileptogenesis by selectively activating pathways such as TrkB signaling." (PMID 27303295, 2016). "One transcript targeted by CREB is the brain derived neurotrophic factor (BDNF), which has been associated to temporal lobe epilepsy in many cases and may serve as a serum marker for epilepsy." (PMID 27855659, 2016). "Taken all the information together, our results demonstrated that miR-155 antagonist might firstly induce the expression of BDNF, which then contributed to the alleviation of epilepsy in the current study." (PMID 27303295, 2016). "In surgically-resected hippocampi from patients with epilepsy, increased levels of BDNF mRNA and protein have been noted, indicating that epileptic activity may up-regulate protein levels via BDNF gene expression." (PMID 27494844, 2016). "Central maladaptive hyperactivities in various brain disorders including pain, Alzheimer, or epilepsy and their enigmatic relationship to BDNF may be revisited in the context of the current findings." (PMID 26476841, 2016). "We investigated the influence of variants in the genes encoding neuron-restrictive silencer factor (NRSF) and brain-derived neurotrophic factor (BDNF), proteins previously associated with cognition and epilepsy, on cognitive function in people with newly diagnosed epilepsy." (PMID 26708060, 2016). "The mechanisms of Npas4 responsible for protecting against epilepsy may regulate GABAergic synapse development through the transcriptional regulation of BDNF." (PMID 25536221, 2014). "Based on these data, it may be hypothesized that BDNF corrects GABAA receptor malfunction phosphorylating GABA subunits whose expression is altered in epilepsy, like the α 1 and the α 4, but also the δ or the γ2." (PMID 23874269, 2013). "It is speculated that pathophysiological levels of BDNF (up or downregulation) may contribute to conditions such as epilepsy or neurodegenerative diseases like Alzheimer’s, Parkinson’s and Huntington’s disease and other neuropsychiatric disorders." (PMID 23840662, 2013). "Evidence suggests that excess BDNF is involved in the pathogenesis of epilepsy, mania and autism." (PMID 23320097, 2013). "Uncontrolled BDNF administration may interfere with these mechanisms and give rise to serious side effects, such as epilepsy." (PMID 24300402, 2013). "These works strongly support a role of BDNF in human epilepsy and raise the possibility that interference with BDNF expression or BDNF action may be a therapeutic strategy for treating epilepsy." (PMID 22654603, 2012). "Additionally, one study has linked BDNF trafficking with FXS symptoms, showing an increased propensity for epilepsy in FXS-afflicted men who have the improperly sorted met-BDNF allele." (PMID 22720171, 2012). "There was no statisticaly significant difference between the epilepsy and control groups for allele frequency of BDNF gene polymorphism (P = 0.738)." (PMID 22654603, 2012). "Similarly, early life stress decreases the expression of brain-derived neurotrophic factor (BDNF) in the adult brain, which is a critical mediator of neuroprotection across epilepsy models." (PMID 21547249, 2011).
epilepsy (continued). "However, the good news is that when scientists administer these eraser medicines for DNA to animals with epilepsy, they observe the brain rewriting its instruction manual: the BDNF gene is reactivated, seizures become less frequent, and depressive behaviors improve." (PMID 40941042, 2025). "Consequently, BDNF/TrkB signaling is involved in the development and progression of epilepsy." (PMID 38006577, 2024). "However, the precise mechanism and role of BDNF in epilepsy is still controversial." (PMID 38006577, 2024). "Thus, interfering with neuronal BDNF signaling and transduction could be a new target against epilepsy and epileptogenesis." (PMID 38006577, 2024). "The increasing BDNF in epilepsy may be due to augmentation of the effect of PGN." (PMID 38006577, 2024). "Therefore, exaggerated autophagy and release of BDNF in epilepsy could explain acceleration of BDNF in relation to epileptogenesis." (PMID 38006577, 2024). "Thus, it is tempting to hypothesize that the involvement in epilepsy of NTFs, specifically BDNF and FGF-2, could go beyond their well-known effects on cell death, neurogenesis, and axonal sprouting, but also include the control of neuroinflammation." (PMID 38673746, 2024). "Furthermore, BDNF is involved in sprouting consequences in epilepsy." (PMID 38006577, 2024). "Consequently, BDNF is involved in epileptogenesis and epilepsy that could be protective or detrimental." (PMID 38006577, 2024). "Furthermore, higher expression of α-Syn in intractable epilepsy could explain the reduction of circulating BDNF in patients with severe and resistant epilepsy." (PMID 38006577, 2024). "In the pilocarpine rat model, however, there was an acetylation upsurge at the brain-derived neurotrophic factor (BDNF) promoter after SE, and induction of c-fos through epileptic processes implies the role of acetylation in controlling mechanisms involved in epilepsy development." (PMID 39845785, 2024). "Consequently; BDNF/TrkB signalling is intricate in the development and progression of epilepsy." (PMID 37737447, 2023). "Therefore, there is a strong controversy concerning BDNF serum levels in epilepsy and its subtypes." (PMID 37737447, 2023). "Furthermore, decreased Kir4.1 channel activity leads to elevated levels of extracellular K+ and glutamate within tripartite synapses, promoting the expression of brain-derived neurotrophic factor (BDNF) by astrocytes, potentially playing a role in the development of epilepsy." (PMID 38067243, 2023). "In epilepsy, the BDNF content may be elevated in the hippocampus." (PMID 38203674, 2023). "DA‐peak regions after BDNF and KCl did not overlap with risk loci for autism and epilepsy, implying that a subset of neuropsychiatric traits might be particularly sensitive to chromatin dynamics upon BDNF and KCl stimulation." (PMID 35996956, 2022). "However, the exact role of BDNF in epilepsy is not fully understood." (PMID 36010576, 2022). "In addition, our present study found that BDNF overexpression in the vlPAG region highly significantly decreased the frequency and duration of spontaneous seizures as well as pain sensitivity in the epilepsy–migraine comorbid rat." (PMID 35557046, 2022). "However, BDNF‐based therapeutic approaches for epilepsy are complicated." (PMID 35557046, 2022). "Moreover, epilepsy-induced alterations in BDNF expression may play a role in engendering the neuropsychiatric comorbidities of epilepsy." (PMID 33815100, 2021). "Therefore, higher serum BDNF in epilepsy patients, correlated with the severity of disease, may reflect adaptations to seizures." (PMID 33802323, 2021). "Thus, the data showed an antiepileptic effect, which suggested that BDNF may promote neuronal cell damage and apoptosis to induce epilepsy formation." (PMID 34899313, 2021).
epilepsy (continued). "It is anticipated that these agents would contribute to alleviating epilepsy by enhancing the K+ buffering function of astrocytes, thereby lowering both [K+]o and [glutamate]o levels in tripartite synapses, and by reducing the astrocyte expression and secretion of BDNF." (PMID 34638578, 2021). "In addition, a variety of epilepsy models have shown that seizures induce transient increase of BDNF in neurons, in spite of the effects of BDNF in the development of behavioral seizures with different kindling paradigms are controversial, according to the previous findings." (PMID 34489702, 2021). "However, activation of the BDNF/TrkB pathway plays an opposite role in epilepsy." (PMID 34425835, 2021). "Meanwhile, BDNF could alleviate the inflammatory response associated with epileptogenesis and thus reduce the disruption of the blood-brain barrier, as well as reduce the number of SRS in an epilepsy model of rats." (PMID 34899313, 2021). "Moreover, human NSCs designed to overexpress BDNF may exhibit therapeutic potential in epilepsy due to their migratory, differentiative, and anti-inflammatory abilities." (PMID 33815100, 2021). "Recently, it has been reported that: compared with the control group, the seizure degree and the peak value of abnormal electroencephalogram (EEG) decreased in the rat model of epilepsy treated with BDNF, which indicated that the sustained low concentration of BDNF could relieve the seizure." (PMID 31049031, 2019). "Furthermore, we previously showed that the inhibition (knockdown or blockade) of Kir4.1 channels facilitated the expression of brain-derived neurotrophic factor (BDNF) in astrocytes, which has long been implicated in the development of epilepsy (epileptogenesis)." (PMID 30813600, 2019). "Overexpression of BDNF may also contribute to the epilepsy-induced cortical network deregulation by increasing even further the plasticity and dendritic branching signaling and causing an overexcitement state of glutamatergic neurons, thus reducing seizure threshold." (PMID 30117106, 2019). "However, the role of BDNF in the development of seizures and epilepsy is somewhat controversial as although there is usually an upregulation of BDNF is associated with a seizure, it is unclear whether this promotes or inhibits seizure development." (PMID 29527169, 2018). "In addition, genetic knockdown of BDNF has been shown to suppress the development of epilepsy." (PMID 29358904, 2017). "Interestingly, it has been shown that increased levels of BDNF mRNA in the temporal cortex of patients with pharmacoresistant epilepsy, and the expression of GR was also influenced in the same direction, implying a converging behavior of BDNF and GR levels in the CNS of some neurological disorders." (PMID 29099059, 2017). "These suggest that DPYSL5 may function in CCD with epilepsy via affecting BDNF and CRMP2." (PMID 28222113, 2017). "Nevertheless, up-regulation of BDNF might also be a contributor to the alleviation of epilepsy." (PMID 27303295, 2016). "In addition, MMP-9 cleavage of pro-BDNF into mature BDNF may play a role in the development of epilepsy through mossy fiber sprouting." (PMID 26283917, 2015). "Moreover, intraventricular infusion of BDNF (1 or 3 μg/h for 1 week) led to spontaneous epilepsy." (PMID 24287913, 2013). "Furthermore, BDNF is upregulated by limbic seizures in animal models and in patients with epilepsy." (PMID 22654603, 2012). "However, an acute and sustained increase in BDNF levels may lead to epilepsy by neuronal overexcitation through mossy fiber budding, and chronic treatment with BDNF can induce synaptic changes that promote neuronal survival and serve to protect the nervous system." (PMID 41327653, 2025). "In particular phospholipase Cγ is a key mediator of the effects of BDNF on hippocampal LTP, and a peptide uncoupling TrkB receptors from phospholipase Cγ1 prevented epilepsy induced by Status Epilepticus in mice." (PMID 40890771, 2025).
epilepsy (continued). "TrkB, on the other hand, is activated by brain-derived neurotrophic factor (BDNF)- and neurotrophin-4 (NT-4)-binding and has been demonstrated in epilepsy studies to function in neural kindling." (PMID 41155675, 2025). "These discoveries about the functions of Bax, Bcl-2, NT4, BDNF, TLR4, NF-κB, and VEGF in epilepsy highlight how critical it is to focus on these pathways in order to create successful treatment plans." (PMID 40540445, 2025). "These discoveries about the functions of Bax, Bcl-2, NT4, BDNF, TLR4, NF-κB, and VEGF in epilepsy highlight how critical it is to focus on these pathways to create successful treatment plans." (PMID 40540445, 2025). "In epilepsy, overactive DNMT enzyme activity represses genes necessary to calm brain signals (e.g., GAD67) and brain cell growth (e.g., BDNF), leading to seizures and mood disturbances." (PMID 40941042, 2025). "Our study suggests that the anti-inflammatory effect of BDNF and FGF-2 in vivo in the epilepsy model was indirect and likely due to a reduction in seizure frequency and severity." (PMID 38673746, 2024). "In addition, overexpression of BDNF in cortical neurons from Sip1 mice resulted in increased expression of Bcl-2, Socs3 and Stat3 genes, which may contribute to the protection of neurons from injury in epilepsy." (PMID 39408863, 2024). "In cases of CDD with early-onset epilepsy, luteolin slows disease progression by suppressing microglial responses, reducing NMDA receptor-induced cell death, and increasing brain-derived neurotrophic factor (BDNF) levels." (PMID 39329119, 2024). "However, BDNF may have a neuroprotective effect against epilepsy." (PMID 38006577, 2024). "In short, flavones exhibit a multifaceted therapeutic impact on epilepsy by engaging with various signaling pathways, such as Nrf2, HO-1, PKA/CREB/BDNF, PI3K/AKT, MAPK, and SIRT1, which are vital for neutralizing oxidative stress." (PMID 39329119, 2024). "In conclusion, chrysophanol demonstrated remarkable neuroprotective and antiepileptic effects at a dose of 10 mg/kg in stress-exacerbated PTZ-induced epilepsy following the TLR4/NFκB -Nrf2/HO-1 and BDNF/VEGF pathways." (PMID 39650161, 2024). "Logistic regression models demonstrated that the probability of FE can be evaluated using GDNF in LF and BDNF in BS; that of MDD using GDNF in LF and cortisol and TNF-α in BS; and that of epilepsy with MDD using GDNF in LF and TNF-α and BDNF in BS." (PMID 38069144, 2023). "The neurospecific proteins BDNF, NSE, VILIP-1, and S100B play an important role in the pathogenesis of neuropsychiatric disorders, including epilepsy." (PMID 38203674, 2023). "Nonetheless, these biomarkers might be taken into account in further studies on epilepsy with a focus on their relation to seizures, which was revealed earlier, or on their interactions with other neurospecific proteins involved in the pathogenesis of epilepsy (e.g., BDNF)." (PMID 38203674, 2023). "The BDNF/TRKB signaling pathway is critical in the pathogenesis and development of various neurological diseases, especially epilepsy." (PMID 36721236, 2023). "Significant correlations between the levels of the neurospecific proteins studied herein suggest interactions between BDNF, NSE, VILIP-1, and S100B in the pathophysiology of epilepsy." (PMID 38203674, 2023). "Our results indicated that epilepsy facilitated migraine through FKN/CX3CR1 axis-mediated microglial activation in the cortex/thalamus/sp5c, which was accompanied by BDNF release." (PMID 35382731, 2022). "Hence we hypothesized that viral induced epilepsy may result from aberrant BDNF signaling." (PMID 35874836, 2022). "BDNF and the tropomyosin kinase receptor B (TRKB) pathway are predicted to function in the prevention or suppression of epilepsy targets." (PMID 36531133, 2022).